RN7SL846P (RNA, 7SL, cytoplasmic 846, pseudogene)
Gene: Miscellaneous RNA gene on chromosome 10 (119,768,247 to 119,768,538, forward strand). Ensembl gene ENSG00000242818.
Homologues: Orthologues: chimpanzee Metazoa_SRP (98% identical), macaque Metazoa_SRP (91% identical). Paralogues in human: RN7SL1 (82% identical), RN7SL2 (82% identical), RN7SL3 (81% identical), RN7SL220P (81% identical), RN7SL597P (80% identical), RN7SL126P (80% identical), RN7SL783P (80% identical), RN7SL566P (79% identical), RN7SL218P (78% identical), RN7SL278P (78% identical), RN7SL559P (78% identical), RN7SL650P (78% identical), and 700 more.